CCL27 (C-C motif chemokine ligand 27)
Diseases named in the same sentence as CCL27 in open-access papers (continued):
Sharing a sentence is not in itself a finding about the gene and the disease.
infection (7 papers, 2018 to 2025). The state of being infected such as from the introduction of a foreign agent such as serum, vaccine, antigenic substance or organism. "In the context of HIV, highly abundant CCL27 may enhance HIV target cell presence, and hence susceptibility to infection." (PMID 31619762, 2020). "This may be because EBV VCA-IgA is produced in the early stage of infection and has a longer half-life than CCL27; indeed, VCA-IgA is present at high concentrations even after EBV is cleared from the body." (PMID 29295705, 2018). "However, at 30 days post-infection, TNF-α, IL-6, KC, CCL3, CCL2, CCL20, CXCL11, CCL11), CCL27, CXCL5, CXCL12 and CCL5 were all significantly higher in the BAL fluid of Duox1 KO compared to WT mice." (PMID 36936954, 2023).
cardiac diseases (2 papers, 2016 to 2017). "CCL27 is known to recruit lymphocytes to cutaneous wounds; it has not yet been demonstrated to play a role in any cardiac diseases." (PMID 27525724, 2016).
bacterial infection (1 paper, 2024). "In the convalescent phase of bacterial infection, CD45RB, CD276, and CCL27 are downregulated." (PMID 37831367, 2024).
kidney diseases (1 paper, 2018). "If true the skin can be targeted for therapeutic manipulations of CCL27 to reduce inflammation in transplant and kidney diseases." (PMID 30214382, 2018). "First the clinical relevance of elevated CCL27 needs confirmation by further studies including patients with native kidney diseases." (PMID 30214382, 2018). "Our finding raises the intriguing possibility of targeting the skin as a mean to inhibit CCL27 and thereby decrease renal inflammation in transplant patients and even in native kidney diseases." (PMID 30214382, 2018).
CCL27 also shares sentences with these, for which no sentence is quoted: contact dermatitis (4 papers); diabetes (3); multiple myeloma (3); pneumonia (3); psoriasis vulgaris (3); allergic contact dermatitis (2); depression (2); dermatitis (2); eczema (2); idiopathic pulmonary fibrosis (2); lung adenocarcinoma (2); lupus (2); non-small cell lung carcinoma (2); systemic sclerosis (2); adenocarcinoma (1); Allergy (1); alopecia areata (1); appendicitis (1); atherosclerosis (1); autoimmune disease (1); autoimmune liver diseases (1); avian influenza (1); bipolar disorder (1); bladder urothelial carcinoma (1); breast invasive carcinoma (1); bronchitis (1); carcinoma in situ (1); chronic obstructive pulmonary disease (1); colonic polyp (1); craniosynostosis (1).
A further 45 diseases each share a sentence with CCL27 in 1 paper.